RNU6-1179P (RNA, U6 small nuclear 1179, pseudogene)
Gene: Small nuclear RNA gene on chromosome 19 (22,555,261 to 22,555,367, forward strand). Ensembl gene ENSG00000207397.
Homologues: Orthologues: chimpanzee U6 (100% identical), pig U6 (82% identical), mouse Gm26439 (79% identical), guinea pig U6 (78% identical), rat LOC120095364 (78% identical), rabbit U6 (76% identical). Paralogues in human: RNU6-144P (92% identical), RNU6-16P (91% identical), RNU6-20P (91% identical), RNU6-333P (91% identical), RNU6-1 (90% identical), RNU6-2 (90% identical), RNU6-25P (90% identical), RNU6-38P (90% identical), RNU6-3P (90% identical), RNU6-4P (90% identical), RNU6-5P (90% identical), RNU6-6P (90% identical), and 1290 more.